NR6A1 (nuclear receptor subfamily 6 group A member 1)
Diseases named in the same sentence as NR6A1 in open-access papers (continued):
Sharing a sentence is not in itself a finding about the gene and the disease.
testicular tumor (1 paper, 2020). "We next detected the microtubule‐associated protein 2 (MAP2), a neuronal cytoskeleton regulator, in testicular tumor xenografts, and found that NR6A1 can promote MAP2 expression." (PMID 33034957, 2020). "We also observed the reciprocal expression between miR‐196‐5p and NR6A1, NR6A1 and E‐cadherin under RA induction, and the data confirmed their regulatory relationship in testicular tumor cells." (PMID 33034957, 2020). "In summary, our findings reveal a novel regulatory pathway of miR‐196a‐5p/NR6A1/E‐cadherin in inhibiting the proliferation, migration, invasion, and neurogenesis of testicular tumor cell in vivo and in vitro, which provides a potential biomarker for targeted TGCTs therapy." (PMID 33034957, 2020). "Since NR6A1 may play a role in neurogenesis of testicular tumors, we next examined the effect of miR‐196a‐5p/NR6A1/E‐cadherin and the correlation of its members in RA induced NT‐2 cells." (PMID 33034957, 2020). "In the present study, we clarified the regulatory pathway of miR‐196a‐5p/NR6A1/E‐cadherin in inhibiting the proliferation, metastasis and neurogenesis of testicular tumor cell in vivo and in vitro, and demonstrated miR‐196a‐5p inhibits testicular tumor progression." (PMID 33034957, 2020). "Thus, our works suggested that NR6A1 may play a role in testicular tumor neurogenesis." (PMID 33034957, 2020). "Further, NR6A1 promoted neuronal marker protein MAP2 expression in RA‐induced neurodifferentiation of NT‐2 cells and testicular tumor xenografts." (PMID 33034957, 2020).
tumor (17 papers, 2013 to 2025). "They reported that NR6A1 expression was significantly associated with the Gleason score (GS) and tumor stage." (PMID 41219936, 2025). "NR6A1 expression was significantly associated with Gleason score (GS) (P=0.003) and tumor stage (P=0.042)." (PMID 28969082, 2017). "More importantly, we found that the patients who had positive NR6A1 expression together with having tumor stage pT3/4 increased risk of biochemical recurrence compared with the other groups." (PMID 28969082, 2017). "Existing studies have reported that NR6A1 is aberrantly expressed in a variety of solid tumors, e.g., hepatocellular carcinoma, gastric carcinoma, and that aberrant expression is closely associated with tumor progression." (PMID 40584630, 2025). "However, NR6A1 expression was significantly associated with Gleason score (GS) (P=0.003), Tumor stage (P=0.042) and Biochemical recurrence (P=0.010)." (PMID 28969082, 2017). "Furthermore, positive NR6A1 expression was found to be associated with GS and tumor stage in PCa." (PMID 28969082, 2017). "NR6A1 acts as a repressor of mTOR activity: low levels of NR6A1 contribute to mTOR activation, favoring the transcription of pro-tumor genes related to lipogenesis, angiogenesis, and NFkB signaling." (PMID 41550951, 2025). "Alterations in metabolism were detected in three tumor cell lines after interference with NR6A1, and the glucose uptake and lactate production of the cells were significantly reduced." (PMID 41219936, 2025). "The results of EdU staining also revealed that NR6A1 siRNA reduced the proliferation rate of the three tumor cell lines." (PMID 41219936, 2025). "CCK8 analysis indicated that NR6A1 siRNA suppressed the proliferative viability of the three tumor cell lines." (PMID 41219936, 2025). "Our research provides preliminary evidence demonstrating a functional role for NR6A1 in tumor glucose metabolism.In the process of glycolysis, HKs are the first enzymes that can convert glucose to glucose 6-phosphate." (PMID 41219936, 2025). "Western blot analysis revealed that, after interference with NR6A1 in the three tumor cell lines, AMPK was the least affected, and the total protein levels and serine phosphorylation (Ser2448) of mTOR were significantly decreased." (PMID 41219936, 2025). "Further investigation is warranted, particularly in vitro and in vivo studies that build on this work by examining NR6A1 protein characteristics, including its regulation, folding, and degradation in tumor cells." (PMID 39624078, 2024). "Prior research into NR6A1/DNMT3A signaling in relation to tumor cell resistance remains limited, with only a few studies addressing this association." (PMID 39624078, 2024). "We found that NR6A1 was upregulated in HCC tumor tissues, and related to accelerated proliferation and poor differentiation grade." (PMID 37903971, 2023). "The data from our animal experiment indicated that the tumor with NR6A1 overexpression gains the neural cell‐like characteristics." (PMID 33034957, 2020). "Based on the character of NT‐2 cells, to further clarify the role of NR6A1 on tumor neurogenesis in vitro, we treated NT‐2 cells for a longer time (21 days) with RA to establish the neural‐like cell model." (PMID 33034957, 2020). "In the future, it may be possible to combine NR6A1-targeted therapy with existing standard treatments, such as chemotherapy or immunotherapy, to synergistically enhance the anti-tumor effect." (PMID 41219936, 2025). "EdU staining and CCK8 analysis revealed that in NR6A1-siRNA-treated cells, the addition of MHY1485 restored the proliferative phenotype of A549 cells to a certain extent, suggesting that NR6A1 promotes tumor cell glycolysis and proliferation via mTOR signaling." (PMID 41219936, 2025).
tumor (continued). "In addition, we found that NR6A1 can affect mTOR signaling, suggesting a broader role in tumor metabolism regulation." (PMID 41219936, 2025). "However, the role of NR6A1 in tumor glucose metabolism is poorly defined and requires additional research." (PMID 41219936, 2025). "Based on our findings, we propose that NR6A1 may orchestrate cellular bioenergetics metabolism across diverse tumor cell types via mTOR signaling." (PMID 41219936, 2025). "We investigated whether NR6A1 interference significantly reduced ATP production in the three tumor cell lines." (PMID 41219936, 2025). "It is highly plausible that NR6A1 modulates mTOR activity through altering tumor cell metabolic states, and mTOR may subsequently regulate cellular metabolism and proliferation." (PMID 41219936, 2025). "Subsequent studies employing integrated metabolic profiling (e.g., oxygen consumption rate detection assays) could comprehensively characterize the role of the NR6A1-mTOR axis in tumor cell metabolic reprogramming." (PMID 41219936, 2025). "Finally, we confirmed that miR‐196a‐5p/NR6A1/E‐cadherin pathway contributes to the inhibition of cell proliferation, migration, invasion, and tumor neurogenesis in TGCTs." (PMID 33034957, 2020). "The results demonstrated that overexpression of NR6A1 significantly promoted tumor growth." (PMID 28969082, 2017). "And overexpression of NR6A1 significantly promoted tumor growth in vivo." (PMID 28969082, 2017). "Therefore, we speculate that mTOR signaling may be the most important mechanism by which NR6A1 regulates tumor cell glycolysis and proliferation." (PMID 41219936, 2025). "Thus, the interaction between miR-99a and NR6A1 in tumor migration and invasion could be a direction for future research." (PMID 33274225, 2020). "Importantly, NR6A1 is reported as an oncogene in HCC: it is up-regulated in HCC patients and associated with a poor prognosis; it promotes cell proliferation, migration, invasiveness, and tumor growth in vitro and in vivo, most likely through the cell cycle, mTOR, WNT, and ERBB signaling pathways." (PMID 39858538, 2025). "We found more than one TA was expressed per tumor, and seven TAs (GPC3, IGF2BP3, NOL4, NR6A1, PKB, PRAME, and SPAG17) were detected in multiple tumors." (PMID 40894019, 2025). "NR6A1 activated glycolysis through p-mTOR signaling and the miR-302a/HK1 axis and ultimately promoted tumor cell proliferation." (PMID 41219936, 2025). "Common changes in differently expressed genes resulted in a significant downregulation of tumor-promoting genes (BCL3, NR6A1, and PFKFB3)." (PMID 38779358, 2024). "To verify the role of NR6A1, OSBP2 and UNC119B in HCC progression, we analyzed the correlation between gene expression and HCC tumor size, pathological grade and clinical stage according to TCGA database." (PMID 37903971, 2023). "However, whether NR6A1 plays a role in tumor neurogenesis and the specific mechanism is unclear." (PMID 33034957, 2020). "After MWA, tumor-promoting genes such as BCL3, Myh10, NR6A1, and PFKFB3 displayed downregulation." (PMID 38779358, 2024). "Additional research is needed to estimate the frequency of NR6A1/DNMT3A inhibition among resistant cancer cells and to delineate the perspective of using the current parameters as an adjunctive prognostic criterion for tumor resistance." (PMID 39624078, 2024). "The tumor immune estimation resource (TIMER) platform was applied to explore the correlation between infiltration levels of immune cells and the expression of four prognosis-related genes (including NR6A1, CXCL5, TGFB1, and C3)." (PMID 36071851, 2022). "Meanwhile, high expression of NR6A1 and MAP2 was positively correlated with lymph node involvement, and high E‐cadherin expression level was negatively correlated with lymph node involvement, tumor size, and metastasis." (PMID 33034957, 2020).
cancer (14 papers, 2013 to 2025). A tumor composed of atypical neoplastic, often pleomorphic cells that invade other tissues. "The increased NR6A1 expression was significantly associated with the Gleason score, advanced pT stage, and cancer cell proliferation." (PMID 38779358, 2024). "Based on the association between NR6A1 expression and the migration and invasion of cancers, we compared the expression of epithelial and mesenchymal markers in cancer cells using Western blotting." (PMID 28969082, 2017). "It is also reported that an increased NR6A1 immunoreactivity was significantly associated with a high Gleason score, advanced pT stage and cancer cell proliferation." (PMID 26005638, 2015). "High levels of Lnc-Nr6a1 are observed in most of the tumors analyzed, which could be associated with the formation of multienzyme complexes and increased glycolytic activity in cancer cells." (PMID 36136852, 2022). "Like most cancer/testis (CT) genes, NR6A1 is expressed mainly in male gonads, repressed in most healthy somatic tissues and derepressed in various somatic malignancies." (PMID 41219936, 2025). "Carnitine palmitoyltransferase 1A (CPT1a), which was upregulated in cancer cells, was also increased by NR6A1 knockdown." (PMID 31315616, 2019). "We demonstrated that NR6A1 plays an oncogenic role, that it activates p-mTOR, and increases the levels of HK1 in these cancer cells." (PMID 41219936, 2025). "We also identified potential transcriptional factors with known oncogenic roles in HCC, e.g. ZEB1, or in other cancer types, e.g. HES1, NR6A1, PATZ1, PAX4 and MTF1, in GE1-HCC." (PMID 33541355, 2021). "ZEB1, HES1, NR6A1, PATZ1, PAX4 and MTF1—have a reported oncogenic role in cancer types other than HCC." (PMID 33541355, 2021). "Considering that NR6A1 can induce the repression of pluripotent genes, we checked the effect of NR6A1 on expressions of cancer stem cell markers in HepG2 cells and did not observe significant changes in cancer stem cell markers." (PMID 31315616, 2019).
infection (1 paper, 2025). The state of being infected such as from the introduction of a foreign agent such as serum, vaccine, antigenic substance or organism. "In the current study, it was shown that levels of gDNA (both beta-actin and NR6A1 DNA) increased in both domestic pigs and wild boar in the late stages of infection with ASFV." (PMID 41471184, 2025). "Assays designed to distinguish between the SNP g.299084751 C > T in the suid genomic NR6A1 gene were able to show large increases in the levels of this genomic DNA in sera from the ASFV-infected suids during the course of the infection, consistent with the changes in beta-actin gDNA." (PMID 41471184, 2025). "In this study, serum samples collected from domestic pigs and wild boar before and at different time points after infection with a highly virulent ASFV were analyzed for the levels of ASFV DNA, gDNA (beta-actin and NR6A1) and mtDNA (mtCytb), as well as for the presence of a cytoplasmic enzyme (LDH)." (PMID 41471184, 2025).
NR6A1 also shares sentences with these, for which no sentence is quoted: breast tumor (2 papers); embryonal carcinoma (2); acute myeloid leukemia (1); adrenal hypoplasia congenita (1); Anophthalmia (1); B-Cell CLL (1); cholangiocarcinoma (1); glioma (1); intrahepatic bile duct cancer (1); lymphoma (1); ovarian carcinoma (1).